EZH2 (enhancer of zeste 2 polycomb repressive complex 2 subunit)
Diseases named in the same sentence as EZH2 in open-access papers (continued):
Sharing a sentence is not in itself a finding about the gene and the disease.
breast cancer (continued). "The published literature has demonstrated that the upregulation of the enhancer of zeste homolog 2 (EZH2), involved in cell cycle regulation, is correlated with tumor invasiveness and aggressive clinical behavior as well as the poor prognosis of breast cancers." (PMID 34298639, 2021). "Here we revealed that EZH2 is necessary for PRMT1 to enhance breast cancer cell proliferation." (PMID 34775498, 2021). "Similarly, in breast cancer cells, phosphorylation of EZH2 by AKT impairs its enzymatic activity, leading to depletion of H3K27me3." (PMID 33741974, 2021). "Tao and colleagues found that EZH2 inhibitors could reactivate TET1 expression in basal-like breast cancer cell lines, indicating that TET1 gene might be epigenetically repressed by H3K27me3 in basal-like breast cancer." (PMID 34885145, 2021). "Thus, combining PARP and EZH2 inhibition represents a promising therapeutic strategy in breast cancer." (PMID 34360879, 2021). "We deduce that STAT3 might regulates EZH2 expression which constitutes the 'vicious cycle' with STAT3 methylation by EZH2 in breast cancer." (PMID 34335938, 2021). "By methylating STAT3, EZH2 improved cell proliferation and migration of breast cancer cells." (PMID 34335938, 2021). "We then knocked down EZH2 in MCF7-PRMT1 cells to detect breast cancer cell proliferation." (PMID 34775498, 2021). "We deduced that EZH2 played the similar role in breast cancer." (PMID 34335938, 2021). "It was shown that knocking down EZH2 could significantly decreased nuclear retention of STAT3 in breast cancer cells." (PMID 34335938, 2021). "Our research also revealed that overexpression of EZH2 enhances breast cancer cell motility." (PMID 34775498, 2021). "Since miR-129-5p expression in various cancer entities (e.g., endometrial cancer, breast cancer and gastric cancer) is mediated by EZH2, an epigenetic modulator of H3K27me3 and DNA methylation, we investigated if EZH2 is mediated by BRAF/MEK pathway inhibition." (PMID 34063443, 2021). "Together with the findings of the previous studies, we suspected that SNHG1 may epigenetically suppress miR-381 expression via recruiting EZH2 in breast cancer cells." (PMID 34806925, 2021). "Chemical and genetic inhibition of EZH2 impeded proliferation and migration of breast cancer cells, which may be partially rescued by STAT3 over-expression." (PMID 34335938, 2021). "Interestingly, our CCK-8 assay results showed that ectopic expression of Flag-EZH2-WT dramatically facilitates breast cancer cell proliferation." (PMID 34775498, 2021). "Apparently, EZH2 reciprocally bound to STAT3 in breast cancer cells." (PMID 34335938, 2021). "In breast cancer, EZH2 also showed increasing expression compared to normal cells and tissues, and could promote oncogenic transformation of primary mammary cells." (PMID 34065631, 2021). "Indeed, a correlation between high EZH2 expression and shorter overall survival was observed in patients with estrogen receptor (ER)-positive breast cancers, while low expression of LOXL4 and high level of miR-30d was associated with good prognosis." (PMID 32754259, 2020). "However, the potential role of EZH2 in driving breast cancer progression still needed further characterization." (PMID 32754259, 2020). "The subsequent studies of the underlying mechanism found that there are some interactions between the DNA methylation and histone modification, such as MAML2, UHRF1, mdig, and EZH2, which directly or indirectly induce the silencing of tumor suppressor genes in breast cancer cells." (PMID 33193750, 2020). "Thus, among different breast cancer types, EZH2 acts as a double-faceted molecule, either as coactivator or corepressor of NF-κB targets, depending on the cellular context." (PMID 33327550, 2020). "In addition, it was shown in breast cancer cells that effective gene re-expression necessitated the inhibition of both G9a and EZH2." (PMID 32537432, 2020).
breast cancer (continued). "However, several studies have shown that the inhibition of EZH2 induces lipid accumulation in hepatocyte cell lines and certain cancer cells such as breast cancer." (PMID 32448308, 2020). "Interestingly, in breast cancer, EZH2 can act as a coactivator via two different mechanisms, depending on the presence or absence of ER." (PMID 33327550, 2020). "Therefore, both EZH2 and JMJD6 proteins are epigenetic regulators, histone modifiers and transcription factors and associate with poorer survival in breast cancer patients." (PMID 33246425, 2020). "Combined assessment of EZH2, LOXL4, miR-29/miR-30d and macrophage infiltration may be a more effective diagnostic method for breast cancer." (PMID 32754259, 2020). "We report for the first time that DANCR essentially contributed to all three malignant phenotypes of breast cancer, which, on the molecular level, was mediated through EZH2‐controlled epigenetic regulation of suppressor of cytokine signaling 3 (SOCS3) via H3K27 trimethylation." (PMID 31860165, 2020). "However, the role of EZH2 as a driving force in breast cancer progression still needs to be characterized." (PMID 32754259, 2020). "H3K27me3 expression was lowest in more aggressive subtypes of breast cancer, specifically the basal-like, triple negative, luminal B, and ER-positive tumors with high proliferation index, similar to EZH2 which was highest in basal-like and triple negative tumors." (PMID 33050946, 2020). "Further, ubiquitination-mediated degradation of EZH2 suppresses breast cancer invasion and metastasis, and O-GlcNAc-modified EZH2 could reverse this degradation." (PMID 33194731, 2020). "Since identification of EZH2 in the research of protooncogene product Vav, studies have shown that EZH2 is highly expressed in tumorigenesis, which regulates the expression of tumor suppressor genes, such as in breast cancer, prostate cancer, and lung cancer." (PMID 33083470, 2020). "Additionally, in ER-negative basal breast cancer, EZH2 activates NF-κB and binds to a set promoter regions by forming ternary complexes with Rel A and Rel B to promote target gene expression and tumorigenesis." (PMID 32448308, 2020). "Moreover, the epigenetic modifier Ezh2 was found to maintain H3K27me3-mediated repression of the FOXC1 gene in Luminal B breast cancer specifically, resulting in the process of metastatic behavior in both a mouse model and patient-derived xenografts." (PMID 33193750, 2020). "EZH2 regulated tamoxifen resistance in breast cancer by the EZH2-ERα-GREB1 transcriptional axis." (PMID 32723346, 2020). "EZH2 itself has been found to be upregulated in breast cancer and promote EMT." (PMID 32257110, 2020). "Collectively, these data suggested that EZH2 was a critical regulator of LOXL4 in breast cancer." (PMID 32754259, 2020). "Blocking of a single molecule may not axe cell proliferation completely and blocking both JMJD6 and EZH2 simultaneously may be more effective in breast cancer patients." (PMID 33246425, 2020). "In addition, our recently study showed that PRMT1 specific inhibitor AMI-1 inhibits breast cancer cell invasion and migration through facilitate EZH2 degradation." (PMID 33308321, 2020). "In addition, our newest study found that PRMT1-mediated R342-EZH2 asymmetric di-methylation (ADMA) strengthens EZH2 stability and promotes breast cancer metastasis." (PMID 33308321, 2020). "An interesting and important point that is highlighted through this review is that higher expression of a PKMT does not necessarily correlate with higher expression of its known histone mark, with a major example being EZH2 and H3K27me3 expression in breast cancer." (PMID 33050946, 2020). "The regulation of EZH2 by O-GlcNAcylation was first reported in breast cancer cells." (PMID 32448308, 2020). "In addition, p38 catalyzing EZH2 phosphorylation at T367 residue elevates its localized to cytoplasm and promotes breast cancer cells distant metastasis." (PMID 33308321, 2020).
breast cancer (continued). "Co-expression of JMJD6 and EZH2 imposed poorer prognosis in breast cancer." (PMID 33246425, 2020). "HIFI-α is a crucial modulator of PRC2/EZH2 in breast cancer." (PMID 33327550, 2020). "Furthermore, EZH2 has been identified as an oncogene, especially in prostate and breast cancers, by epigenetically impeding the expression of various tumor suppressor genes 10-12." (PMID 32754259, 2020). "lncRNA ANCR regulates breast cancer progression and metastasis by reducing the stability of EZH2." (PMID 33511127, 2020). "Furthermore, SCF E3 ubiquitin ligase β-TrCP reduces EZH2 stability and H3K27me3 occupation through mediating EZH2 ubiquitination-proteasome degradation in breast cancer cells." (PMID 33308321, 2020). "In breast cancer (BC) cells, EZH2 promotes expansion of TICs and mammosphere formation through activation of RAF1/β-catenin signaling, while in glioblastoma loss of H3K27me3 can lead to aberrant Wnt signaling activation, which is necessary for maintenance of CSCs." (PMID 33322354, 2020). "EZH2 expression has also been correlated to invasiveness in laryngeal or breast carcinoma." (PMID 33291363, 2020). "Interestingly, we found that HOTAIR and EZH2 were highly co-expressed in TERT mutations only subtype of glioma and triple-negative subtype of breast cancer." (PMID 31367244, 2019). "Moreover, we revealed that LINC01133 inhibited invasion and metastasis in breast cancer, partly through binding with EZH2 to mediate SOX4 transcriptional inhibition." (PMID 31557401, 2019). "O-GlcNAcylation of EZH2 was first evidenced in breast cancer MCF7 cells." (PMID 30873122, 2019). "Additionally, we demonstrated that HOTAIR and EZH2 are highly co-expressed in TERT Mutation Only subtype of glioma and triple-negative subtype of breast cancer." (PMID 31367244, 2019). "Here, in contrast, we show that Ezh2 is required for tumor progression beyond an early hyperplastic stage in models of ErbB2-positive breast cancer and for proliferation and tumor growth in established ErbB2+ breast cancers." (PMID 31263101, 2019). "Much attention is paid to understand the role of EZH2 in breast cancer and how it can be targeted." (PMID 30760814, 2019). "We investigated the influence of EZH2/1 restriction on cell motility and EMT to determine whether the EZH2/NF‐κB/NKILA signaling axis can be manipulated to enhance therapeutic intervention in breast cancer." (PMID 31282094, 2019). "Although functions of identified EZH2 target genes are known, their role and regulation in cancer is not well studied and may prove to be a therapeutic target in breast cancer treatment." (PMID 30760814, 2019). "In contrast, non‐specific inhibition of EZH2/1 in ER+ breast cancer cells may induce a more robust response over tazemetostat delivery alone, as EZH1 may negatively regulate NKILA under EZH2 inhibition." (PMID 31282094, 2019). "EZH2 is highly expressed in multiple cancers, including glioblastoma and breast cancer." (PMID 30655550, 2019). "Depletion of ZRANB1 in breast cancer cells results in EZH2 destabilization and growth inhibition." (PMID 30150556, 2018). "Abnormally elevated EZH2 level may be a promising biomarker for aggressive breast cancers with poor prognosis." (PMID 29864144, 2018). "However, EZH2 and H3K27me3 show an inverse correlation across breast cancer subtypes, the EZH2 expression is the highest and the H3K27me3 is the least in TNBC tumors compared to other subtypes." (PMID 30547810, 2018). "Thus, polycomb group protein EZH2 plays a significant role in NIC-mediated increased breast cancer progression." (PMID 29396474, 2018). "The observation that Suz12 deficiency in normal mammary cells leads to de-repression of cdkn2a, paralleling that seen with loss of Ezh2, would predict that loss of PRC2 function in breast cancer would result in decreased tumor proliferation via up-regulation of p16Ink4a and p14Arf expression." (PMID 30080881, 2018).
breast cancer (continued). "However, direct demonstration that p38α phosphorylates EZH2 in solid tumors, the biological consequences of EZH2 T367 phosphorylation in breast cancer, and the mechanisms of pEZH2(T367) function are still unclear." (PMID 30022044, 2018). "To determine whether p38 activation was required for EZH2-vinculin binding in breast cancer cells, we induced p38 MAPK signaling in MDA-MB-231 cells using the tetON-HA-MKK6EE system." (PMID 30022044, 2018). "Polycomb group protein EZH2 is overexpressed in ER- breast cancer, promoting metastasis." (PMID 30022044, 2018). "Lee ST and colleagues identified that EZH2 binds to the NF-κB components to form a ternary complex leading to transcriptional activation of its downstream target genes in ER-negative basal-like breast cancer cells." (PMID 29556394, 2018). "Indeed, deletion of Ezh2 accelerated tumors in a mouse model of Brca1-deleted breast cancer and in a breast cancer model of Notch activation." (PMID 30080881, 2018). "Then we investigated whether CUL1 exerted its effect on breast cancer cells metastasis through EZH2." (PMID 30578411, 2018). "The association of NIC with a high level of EZH2 was confirmed in vitro in both cancerous and non-cancerous breast cancer cell lines." (PMID 29396474, 2018). "To investigate whether p38α phosphorylates EZH2 at T367 in breast cancer and study the biological relevance, we developed and validated a rabbit polyclonal anti-phosphorylated T367 EZH2 antibody." (PMID 30022044, 2018). "The present study reveals a previously undescribed oncogenic mechanism by which p38-mediated EZH2 phosphorylation at T367 promotes breast cancer progression by inducing EZH2 cytoplasmic function and reducing nuclear EZH2 methyltransferase activity on histone H3K27." (PMID 30022044, 2018). "We demonstrate that higher FOXC1 is predictive of favourable outcome specifically in Luminal B breast cancer patients and establish the use of EZH2 methyltransferase inhibitors as a viable strategy to block metastasis in Luminal B breast cancer, where options for targeted therapy are limited." (PMID 29959321, 2018). "EZH2 rs12670401 and EZH2 rs6464926 polymorphisms, age of menarche, and menopausal status were risk factors for breast cancer (all P<0.05), but age was not the risk factor of breast cancer (P>0.05)." (PMID 29089464, 2018). "Our study found that C allele of EZH2 rs12670401, T allele of EZH2 rs6464926, and 3 allele of SMYD3 VNTR could increase the susceptibility to breast cancer." (PMID 29089464, 2018). "Data obtained in breast cancers also illustrated the dual role of EZH2 in cancer aggressiveness." (PMID 34991274, 2018). "Present study investigates the role of EZH2 in regulation of ERRs in breast cancer." (PMID 29940916, 2018). "Moreover, EZH2 physically bridged the estrogen receptor (ER) and components of Wnt signaling to induce the gene expression in breast cancer cells." (PMID 30064416, 2018). "Based on our study, targeting this oncogenic mechanism in a subset of ER- breast cancers with high pEZH2(T367) expression using combined EZH2 and p38 inhibition may offer a therapeutic opportunity to interrupt breast cancer metastasis to distant sites." (PMID 30022044, 2018). "Similarly, high levels of EZH2 expression correlate with an adverse prognosis in solid tumors, such as prostate and breast cancer." (PMID 28758948, 2017). "Overall, these data suggest that the IGF1/X10 enhanced tumor formation is associated with several key candidate cancer drivers that could contribute, including Ezh2 and Hras which are known drivers in human breast cancer." (PMID 28173837, 2017). "For instance, the level of EZH2 is low in CSCs in hepatocarcinoma and breast cancer." (PMID 28415635, 2017).
breast cancer (continued). "Growing evidence showed that EZH2 is upregulated in a wide spectrum of solid tumors including non-small cell lung cancer, prostate cancer, head and neck squamous cell carcinoma, breast cancer, liver cancer, and gastric cancer." (PMID 27880940, 2017). "In addition, p57 is also a direct target of EZH2 and repressed by serveral epigenetic mechanisms in ovarian cancer, breast cancer and non-small cell lung cancer." (PMID 29262540, 2017). "In addition, p57 is also a direct target of EZH2 and repressed by several epigenetic mechanisms in ovarian cancer, breast cancer and non-small cell lung cancer." (PMID 29262540, 2017). "However, EZH2 acts in an opposite manner in ER-positive luminal-like breast cancer cells and represses NF-κB target gene expression by interacting with ER and directing repressive histone methylation on the promoters of NF-κB target genes." (PMID 28758948, 2017). "Interestingly several X10/IGF1-enriched mutations were observed, including Ezh2, Hras, and Traf7, of which Ezh2 and Hras are prominent modulators of human breast cancer." (PMID 28173837, 2017). "EZH2 also activated NF-κB targets of NOTCH1 in breast cancer cells." (PMID 28410242, 2017). "Although it remains unknown whether BPA affects EZH2 expression during spermatogenesis, it did so in both cultured breast cancer cells and mouse mammary." (PMID 28582417, 2017). "In contrast, two N-terminal domains of EZH2 interacts directly with β-catenin and estrogen receptor alpha (ERα), and thus links the Wnt and estrogen signaling pathways, leading to gene transactivation and cell cycle progression in breast cancer cells." (PMID 28561778, 2017). "This argument could be supported by the findings that EZH2 binds Wnt effector β-catenin and promotes transcriptional activation of genes in breast cancer cells." (PMID 29156711, 2017). "Previously, EZH2 has been reported to be essential for CSCs of glioblastoma and breast cancer." (PMID 27926488, 2017). "We examined the change in expression of EZH2 between primary and metastatic lesions, the correlation between the expression of EZH2 and the expression of other biomarkers, and the relationship between EZH2 expression and patient outcome in metastatic breast cancer." (PMID 28241804, 2017). "Wang and colleagues showed that EZH2 was predictive for poor OS in breast cancer patients." (PMID 27880940, 2017). "Because the expression of EZH2 was similar in canine mammary carcinoma and human breast cancer, spontaneous canine mammary tumors may be a suitable model for studying EZH2 and treatment development." (PMID 27502594, 2016). "We also confirmed that H19 bound to EZH2 in breast cancer cells." (PMID 27845892, 2016). "However, in breast cancer, EZH2 acts as a dual-function transcriptional regulator with dynamic activity by transactivating estrogen and Wnt pathways via physically interacting directly with estrogen receptor and β-catenin to promote cell cycle progression." (PMID 27092879, 2016). "EZH2 overexpression was first reported in prostate and breast cancer." (PMID 27019355, 2016). "We have also reported that curcumin inhibited EZH2 expression in breast cancer cells." (PMID 27049834, 2016). "EZH2 protein showed a higher expression level in grade 3 than grade 1 mammary cancers." (PMID 27502594, 2016). "Similar results were obtained for other breast cancer and EZH2 mutant lymphoma cell lines." (PMID 26868841, 2016). "However, current studies of EZH2 in cancer limited in hormonal tumors such as prostate cancer and breast cancer." (PMID 27835578, 2016). "In particular, EZH2 has been connected to the aggressiveness of breast cancer." (PMID 27502594, 2016). "As the CMTs in our current study in a canine model showed similarities to human breast cancers in terms of EZH2 expression, we suggest that dogs with naturally occurring CMTs could be used as animal models in future clinical trials." (PMID 27502594, 2016).